ERBB3 (erb-b2 receptor tyrosine kinase 3)
Diseases named in the same sentence as ERBB3 in open-access papers (continued):
Sharing a sentence is not in itself a finding about the gene and the disease.
triple-negative breast carcinoma (31 papers, 2012 to 2025). An invasive breast carcinoma which is negative for expression of estrogen receptor (ER), progesterone receptor (PR), and human epidermal growth factor receptor 2 (HER2). "The neutralization of the NRG1β/ERBB3/ERBB2 axis deserves further studies as a therapeutic strategy for basal-like/triple-negative breast cancers, which today have very limited treatment opportunities." (PMID 35406375, 2022). "In accordance, triple-negative breast cancer exhibits low expression levels of ERBB3 compared to the other clinical subtypes." (PMID 35406375, 2022). "Overall, our data unveil that the NRG1β/ERBB3/ERRB2 axis promotes cell growth in suspension of basal-like/triple-negative breast cancer cells and that this process is efficiently prevented by the administration of anti-ERBB2 agents, in particular, pertuzumab." (PMID 35406375, 2022). "Despite ERBB3/HER3 and its partner ERBB2/HER2 showing low expression levels in basal-like/triple-negative breast cancers, stratification of basal-like patients according to ERBB3 mRNA expression levels highlighted a correlation between higher ERBB3 levels and shorter relapse-free patients’ survival." (PMID 35406375, 2022). "That was the case for BRCA1, ERBB2 and ERBB3 loci that were found to be deregulated in triple-negative breast cancers or von Hippel-Lindau (VHL) tumour suppressor gene and PRCC that was linked to clear cell renal cell carcinoma and papillary renal cell carcinoma respectively." (PMID 31105870, 2019). "Despite ERBB3 expression in basal-like/triple-negative breast cancer appearing to be low, our study suggests that the NRG1β/ERBB3/ERBB2 axis in basal-like/triple-negative breast cancer patients may support tumor cell dissemination by promoting anchorage-independent cell growth." (PMID 35406375, 2022). "However, our unpublished data indicated that triple-negative breast cancer cells that express NRG do not express ErbB3 or ErbB2." (PMID 36511917, 2023). "In vitro analyses unveiled that the activation of the NRG1/ERBB3/ERBB2 axis robustly induces anchorage-independent growth of basal-like/triple-negative breast cancer cellular models, without significant effects on cell proliferation, differentiation, and migration in adhesion." (PMID 35406375, 2022).
lung adenocarcinoma (30 papers, 2011 to 2026). A carcinoma that arises from the lung and is characterized by the presence of malignant glandular epithelial cells. "Jaiswal and colleagues reported oncogenic ERBB3 mutations were present in approximately 1% of lung adenocarcinoma from a Western cohort." (PMID 26486077, 2015). "ErbB3 was shown to be highly expressed in lung adenocarcinomas and associated with poor prognosis as measured by immunohistochemistry." (PMID 22889873, 2012). "In a gene expression study of 10 ‘signature’ genes in early lung adenocarcinoma, a two-gene signature, comprising only ERBB3 and BRCA1 expression was an independent risk factor in predicting survival, improving the discriminatory power of conventional classification systems." (PMID 34274969, 2021). "We consulted the RNA-seq datasets of the TCGA database and noticed CNOT3 expression was positively correlated with the expression of some ErbB family of receptor tyrosine kinases such as EGFR, ErbB-2 (neu, HER2) and ErbB-3 (HER3) in lung adenocarcinoma." (PMID 37919290, 2023). "In summary, our study shows that conditional ERK3 overexpression cooperates with PTEN deletion to promote the formation of lung adenocarcinoma at least partially by upregulating NRG1/ERBB3 signaling." (PMID 34719109, 2022). "In the present study, we have found that conditional overexpression of ERK3 in lungs cooperates with PTEN deletion to promote the formation of lung adenocarcinoma at least partially owing to upregulation of NRG1/ERBB3 signaling." (PMID 34719109, 2022). "Hsa_circ_0012673 is able to sponge miR-22, which targets ERBB3/HER3, an important receptor tyrosine kinase in lung adenocarcinoma." (PMID 33976116, 2021). "In contrast to circ-ITCH, hsa_circ_0012673 is overexpressed in lung adenocarcinoma and promotes cell proliferation through the miR-22/ErbB3 pathway." (PMID 33976116, 2021). "ROR1 is also required to sustain the association between EGFR and receptor tyrosine-protein kinase erbB-3 (ERBB3), the activation of ERBB3, consequentially, making ROR1 an ideal target for therapies against EGFR-TKI resistance in lung adenocarcinoma." (PMID 31452776, 2019). "The circRNA hsa_circ_0012673 is a sponge for miR-22 and releases the inhibition of target gene, human epidermal growth factor receptor 3 (HER3/ErbB3), thereby promoting the proliferation of lung adenocarcinoma cells." (PMID 30996117, 2019). "According to results, the overexpression of ERBB2 and ERBB3 reduced the probability of survival of clinical patients with lung adenocarcinoma." (PMID 31619200, 2019). "Hsa_circ_0012673 participates in the proliferation of lung adenocarcinoma through the miR-22/ErbB3 pathway." (PMID 30400981, 2018). "This article describes the regulatory role of the hsa_circ_0012673/miR-22/ErbB3 pathway in proliferation and provides a new idea for the diagnosis and treatment of lung adenocarcinoma." (PMID 30400981, 2018). "Hsa_circ_0012673 functions as a miRNA sponge of miR-22, which targets erb-b2 receptor tyrosine kinase 3 (ErbB3), promoting lung adenocarcinoma (LAC) cell proliferation." (PMID 30111313, 2018). "Results showed that DNA copy number abundances of EGFR, ERBB2, ERBB3, and ERBB4 had associations with overall survival in lung adenocarcinoma with EGFR-activating mutations." (PMID 26824984, 2016). "In this paper we first show, by using a set of malignant pleural effusion derived cell cultures (MPEDCC) from patients with lung adenocarcinoma, that surface ErbB3 expression correlates with increased AKT phosphorylation." (PMID 23896512, 2013). "In order to identify a lung adenocarcinoma cell system suitable to study the efficacy of our anti-ErbB3 monoclonal antibodies we screened several cells for surface ErbB3 expression." (PMID 23896512, 2013). "The high expression of ErbB3 on the surface of a subset of lung adenocarcinoma cell cultures led us to explore the effect of anti-ErbB3 monoclonals directed against the extracellular domain of the receptor." (PMID 23896512, 2013).
lung adenocarcinoma (continued). "ErbB3 was constitutively activated at high level in several lung adenocarcinoma cell lines, which also express HER2." (PMID 22889873, 2012). "In vivo, ERBB3 is repressed in lung adenocarcinoma tissue with elevated ZEB1 expression." (PMID 27456471, 2016). "Afatinib is an irreversible inhibitor of the ERBB receptor family (including EGFR, HER2, ERBB3, and ERBB4), and has been approved for the treatment of advanced lung adenocarcinoma." (PMID 39406703, 2024). "In this study, EGFR-activating mutation status and DNA copy number abundances of EGFR, ERBB2, ERBB3, and ERBB4 were measured in 261 surgically resected lung adenocarcinomas." (PMID 26824984, 2016). "We previously noted that the knockdown of HNF4A in lung adenocarcinoma cell lines suppressed the expression and phosphorylation of ERBB3 (data not shown)." (PMID 38710944, 2025). "However, a study assessing CNVs in ErbB genes found that half of all lung adenocarcinomas have CNVs of EGFR, ERBB2, ERBB3 and ERBB4, with higher CNV number corresponding to poorer prognosis." (PMID 34274969, 2021). "A signaling pathway involving EGFR, ErbB2, ErbB3, phosphatidylinositol 3-kinase (PI3K), Akt, glycogen synthase kinase 3- β (GSK3-β), and cyclin D1 is essential for the maintenance of survival, mitosis, and invasiveness of human lung adenocarcinoma cell lines as well as to evade apoptosis." (PMID 22724003, 2012).
cervical carcinoma (23 papers, 2017 to 2026). A carcinoma arising from either the exocervical squamous epithelium or the endocervical glandular epithelium. "HER3 (ERBB3) is overexpressed in a subset of cervical cancers and is associated with PI3K/AKT–mediated resistance, making it an attractive biomarker-selected target." (PMID 41590369, 2026). "The hotspot mutation site of ERBB3 in cervical cancer is extracellular domain V104M/L, the one has been shown to be a statistically significant mutation hotspot to promote oncogenic signalling." (PMID 35581263, 2022). "ERBB3 modulates PI3K/Akt/mTOR pathway activation to alter the epithelial–mesenchymal transition in cervical cancer." (PMID 39075562, 2024). "According to our previous findings of ERBB3 sequencing of cervical cancer cell lines, the mRNA levels of different primary cervical cancer cell lines indicated that ERBB3 is highly expressed in cervical malignant cell lines dominated by SiHa and HeLa." (PMID 36911370, 2023). "It was revealed that in cervical cancer the ERBB3 gene was enriched in the PI3K/AKT signaling pathway (NES=-1.707, P=0.045, FDR=0.034)." (PMID 36911370, 2023). "The high expression of ERBB3 in cervical cancer tissues (especially HPV-positive and adenocarcinoma-related) promoted the activation of the PI3K/AKT/mTOR pathway." (PMID 36911370, 2023). "The mRNA levels of different primary cervical cancer cell lines indicate that ERBB3 is highly expressed in cervical malignant cell lines dominated by adenocarcinoma: AV3, Hela." (PMID 35581263, 2022). "Chemokines CXCL19 and chemokine receptors CXCR5 mediate immune cell trafficking into the tumour micro environment based on the DNA methylation of ERBB3 in cervical cancer." (PMID 35581263, 2022). "Our study indicated ERBB3 is more likely to be a carcinogenic factor than a key prognostic factor for cervical cancer." (PMID 35581263, 2022). "In this study, it was found that in ERBB family, the expression of ERBB3 in cervical cancer tissues was higher than that in normal tissues." (PMID 35581263, 2022). "Through further GO and KEGG clustering analysis of the functions of these three factors (YTHDC1, YTHDC2 and RBM15), we infer that ERBB3 methylation plays an important role in the occurrence and progression of cervical cancer." (PMID 35581263, 2022). "Further experiments will verify the carcinogenic mechanism of this methylation site on ERBB3 in cervical cancer." (PMID 35581263, 2022). "For example, PIK3CA was an inclusion criterion in one clinical trial (NCT02957266) for directing cervical carcinoma therapy, as well as, ERBB3 and FBXW7 were considered as biomarkers in several clinical trials for malignant solid tumor." (PMID 34221990, 2021). "One recent study of 228 cervical cancers using TCGA data identified SHKBP1, ERBB3, CASP8, HLA-A, and TGFBR2 as novel significantly mutated genes, and previously identified pathogenic genes including PIK3CA, EP300, ARID1A, and NFE2L2 were also confirmed." (PMID 28390392, 2017). "Also, the PI3K/AKT/mTOR pathway, mediated by ERBB3, plays a role in altering the epithelial–mesenchymal transition in cervical cancer." (PMID 38067297, 2023). "One of the largest cervical cancer sequencing efforts—The Cancer Genome Atlas (TCGA) Project—reveals novel mutations in several genes, including SHKBP1, ERBB3, CASP8, HLA-A and TGFBR2, amplifications in immune targets PD-L1 and PD-L2, by sequencing 228 primary cervical cancer patients." (PMID 35205332, 2022). "MiR-152 suppresses the proliferation, migration and infiltration of cervical cancer cells and reduces their resistance to DDP chemotherapy by inhibiting the expressions of proteins in the ERBB3/Akt/c-myc and ERBB3/Akt/Snail pathways." (PMID 38223603, 2023). "When ERBB3 activates the PI3K pathway to change immune cell infiltration, the cervical cancer prognosis model is meaningful." (PMID 36911370, 2023). "Therefore, we speculate that ERBB3 is a pathogenic factor of cervical cancer rather than a prognostic factor." (PMID 35581263, 2022).
cervical carcinoma (continued). "The low expression of ERBB3 in HPV(–)-C33A inspired us to study the significance of ERBB3 and HPV in the carcinogenicity of cervical cancer in the future." (PMID 35581263, 2022). "A landmark multi-omic analysis by The Cancer Genome Atlas (TCGA) provided a comprehensive molecular characterization of cervical cancer, identifying APOBEC-driven mutagenesis as a dominant process and recurrent alterations in PIK3CA, PTEN, KRAS, ERBB3, CASP8, HLA-A, SHKBP1, and TGFBR2." (PMID 41590369, 2026). "The current study intended to explore how ERBB3 mediates the PI3K/AKT/mTOR pathway and changes the tumor immune microenvironment to affect the EMT status of cervical cancer, which may provide further understanding of MMPs involved in immunotherapy." (PMID 36911370, 2023). "We uncovered that genetic alterations in PIK3CA, PTEN, ERBB3, and PI3K/AKT pathway, as well as TMB, could be novel predictive biomarkers in patients with cervical cancer treated with PD-1 inhibitor combination therapy." (PMID 34011535, 2021). "In summary, we uncovered that genetic alterations in PIK3CA, PTEN, ERBB3, and PI3K/AKT pathway could be novel predictive biomarkers in patients with cervical cancer treated with PD-1 inhibitor combination therapy." (PMID 34011535, 2021). "It shows that ERBB3 may bes closely related to adenocarcinoma and HPV positive cervical carcinoma." (PMID 35581263, 2022). "Previous studies showed that MMP9 alone did not significantly affect the survival rate of cervical cancer; however, in the present study, when TME macrophages decreased, there was an impact on OS, and the OS with high ERBB3 was significantly reduced." (PMID 36911370, 2023). "We also observed a strong signal in HeLa, a uterine cervix cancer cell line characterised by the absence of ErbB3 receptor on the cell surface and in MCF-7 known to express ErbB3 on the plasma membrane." (PMID 35255831, 2022).
head and neck squamous cell carcinoma (23 papers, 2011 to 2025). A squamous cell carcinoma that arises from any of the following anatomic sites: lip and oral cavity, nasal cavity, paranasal sinuses, pharynx, larynx, and salivary glands. "ErbB3 has been associated with decreased survival in head and neck squamous cell carcinoma, and an anti-ErbB3 mAb has shown promising initial clinical activity." (PMID 36362284, 2022). "Interestingly, resistance to anti-ErbB3 treatment in head-and-neck squamous cell carcinoma is associated with increased Trop2 protein expression." (PMID 33187148, 2020). "CDX-3379, an anti-ErbB3 monoclonal antibody, showed promising molecular and antitumor activity in head and neck squamous cell carcinoma (HNSCC) as a monotherapy or in combination with cetuximab." (PMID 36551663, 2022). "In phase I development, CDX-3379, an anti-ErbB3 monoclonal antibody, showed promising molecular and antitumor activity in head and neck squamous cell carcinoma (HNSCC), alone or in combination with cetuximab." (PMID 35625959, 2022). "A significant tumor specific overexpression of all four ErbB receptors including EGFR, ErbB2, ErbB3, and ErbB4 has been reported in head and neck squamous cell carcinomas (HNSCC)." (PMID 24886178, 2014). "Another report provided evidence that the growth of head and neck squamous cell carcinomas (HNSCC) were reduced in PDX mice by dual targeting of EGFR and ErbB3." (PMID 28417948, 2017).
hepatocellular carcinoma (22 papers, 2006 to 2026). A malignant tumor that arises from hepatocytes. "We evaluated the diagnostic and prognostic value of serum ERBB3 measurement in hepatitis C virus (HCV)-infected patients with early hepatocellular carcinoma (HCC)." (PMID 33799723, 2021). "Here we investigate the potential clinical utility of the measurement of serum epidermal growth factor receptor 3 (i.e., ERBB3) in hepatitis C virus-infected patients with early hepatocellular carcinoma." (PMID 33799723, 2021). "MiR-17-5p directly targets ERBB3 and suppresses postoperative metastasis of hepatocellular carcinoma." (PMID 34552925, 2021). "Conversely, in patients with early HCC, serum ERBB3 values were significantly associated with overall survival, suggesting that the biomarker may be useful to tailor appropriate treatment strategies in hepatitis C virus (HCV)-infected patients with early hepatocellular carcinoma." (PMID 33799723, 2021). "Telmisartan reportedly decreased ErbB3 in hepatocellular carcinoma." (PMID 31261874, 2019). "Similarly, changes in cell cycle regulating genes in TRPC1-silenced cells indicate possible cell cycle arrest along with compensatory up-regulation of ERBB3 growth factor receptor—amongst others—to maintain hepatocellular carcinoma cell proliferation." (PMID 27443843, 2016). "Median values of serum ERBB3 were similar between patients with cirrhosis and those with early hepatocellular carcinoma (HCC); therefore, the measurement of the biomarker in the setting of HCC surveillance appeared unsuitable." (PMID 33799723, 2021). "Experiments were performed using three hepatocellular carcinoma (HCC) cell lines, Hep3B, HepG2 and PLC/PRF/5, expressing various levels of EGFR, ErbB2 and ErbB3." (PMID 32515546, 2020). "Conclusion: miR-17-5p and miR-20a-5p could suppress postoperative metastasis of hepatocellular carcinoma via blocking HGF/ERBB3-NF-κB positive feedback loop and offer a new probable strategy for metastasis prevention after HCC resection." (PMID 32206115, 2020). "Growth factor receptor ERBB3 and transforming growth factor alpha (TGF-α) were recently shown to act as compensatory survival factors that increased after c-Met inhibition in hepatocellular carcinoma cells." (PMID 27443843, 2016).